IL6 (interleukin 6)
Diseases named in the same sentence as IL6 in open-access papers (continued):
Sharing a sentence is not in itself a finding about the gene and the disease.
pulmonary fibrosis (continued). "A role for IL-6 trans-signaling in IPF was suggested as elevated sIL-6R levels were found in the lungs of patients with IPF and of mice with bleomycin-induced pulmonary fibrosis." (PMID 31694340, 2019). "The lung fibrosis-related cytokines IL-6 and IL-33 were significantly increased in the blood of mice with BLM-induced lung injury by day 14 compared with the control mice, indicating that IL-6 and IL-33 may associate with lung injury and muscle wasting in BLM-induced lung fibrosis mouse models." (PMID 31049028, 2019). "DHP mainly regulated pulmonary fibrosis-related inflammatory genes and signaling pathways, such as IL1β, IL4, IL5, IL6, TGFβ1, and TNFα." (PMID 31105564, 2019). "Parallel studies in fibroblasts derived from patients with idiopathic pulmonary fibrosis showed similar increases in IL7AS levels, that also negatively regulate IL-6 release." (PMID 30619270, 2018). "These cells secrete pro-inflammatory and pro-fibrotic cytokines and chemokines, including IL-1β, IL-6, TNF-α, and MCP-1, which influence the pathogenesis of pulmonary fibrosis." (PMID 30250465, 2018). "In accordance with the present findings, UCMSC administration decreased inflammation and inhibited the expression of IL-1, IL-6, TNF, collagen I, and TGF-β in bleomycin-induced lung fibrosis in mice." (PMID 29954457, 2018). "In lung fibroblasts from patient with idiopathic pulmonary fibrosis (IPF), IL-6 was shown to induce resistance to FAS ligand-mediated apoptosis; however, normal lung fibroblasts were sensitive to FAS ligand-induced apoptosis." (PMID 30081609, 2018). "IL-1β can drive the progression of pulmonary fibrosis, and it is known to mediate the release of other inflammatory cytokines such as TNF-α and IL-6." (PMID 30087305, 2018). "In vivo experiments showed that BLM combined with SCU in the treatment of mice bearing H22 ascites tumor prolonged the survival time, alleviated BLM-induced pulmonary fibrosis, reduced the production of TNF-α; IL-6, and the levels of MDA and MPO." (PMID 29962947, 2018). "In this study, bleomycin-induced pulmonary fibrosis was characterized by increases in CTGF, TGFβ1, ET-1, IL-6, and IL-13, as profibrotic mediators." (PMID 29409529, 2018). "In order to assess the therapeutic effects of PFD, fibrosis-related factors IL-6 and COL1A1 levels in MLF supernatant induced by TGF-β1, as well as those in serum and BALF of mice with BLM-induced pulmonary fibrosis were estimated." (PMID 28420366, 2017). "In conclusion, the gp130 cytokines IL-6 and OSM contribute to the accumulation of profibrotic macrophages and enhancement of bleomycin-induced lung fibrosis." (PMID 29038604, 2017). "Several proinflammatory cytokines, including MCP-1 and IL-6, are involved in pulmonary inflammation and the development of BLM-induced pulmonary fibrosis in mice." (PMID 28049526, 2017). "The pro-inflammatory cytokines are known to play a significant role in the processing of pulmonary fibrosis, including TNF-α and IL-6." (PMID 28245556, 2017). "To evaluate the anti-inflammatory and anti-fibrotic effects of CNP against BLM-induced lung fibrosis in periostin-CNP Tg mice, we analyzed the mRNA expression changes of IL-1β, IL-6, bFGF, TGF-β, TIMP1, and collagen 1A." (PMID 26895702, 2016). "IL-6 is a pleiotropic cytokine and functions as a proinflammatory factor as well as a profibrotic factor in BLM-induced lung fibrosis." (PMID 26289430, 2015). "We found that lung IL-6 and TNF-α levels were significantly increased after BLM administration in the BLM–induced murine pulmonary fibrosis model." (PMID 26497260, 2015). "It is well known that increased expression levels of the proinflammatory cytokines IL-6, IL-1β and TNF-α and decreased expression levels of the anti-fibrotic cytokine IFN-γ are involved in the pathogenesis and progression of pulmonary fibrosis." (PMID 25092105, 2014).
pulmonary fibrosis (continued). "When challenged with bleomycin, the gp130757F transgenic mice exhibited an increase in lung fibrosis, COL1, and IL-6 expression when compared to wild type, bleomycin-challenged mice." (PMID 24478703, 2014). "Basic pharmacological studies confirmed that dexamethasone can regulate gene transcription and expression of a variety of inflammatory cytokines, such as IL-6, TNF-α, and TGF-β, which is closely related to radiation-induced lung fibrosis." (PMID 24744681, 2014). "Although the mechanisms by which PN attenuates lung fibrosis are unclear, this study shows that TNF-α and IL-6 cytokine levels are significantly reduced by PN in alveolar macrophage culture." (PMID 21423633, 2011). "Iloprost prevents bleomycin-induced pulmonary fibrosis, possibly by upregulating antifibrotic mediators (IFNγ and CXCL10) and downregulating pro-inflammatory and pro-fibrotic cytokines (TNFα, IL-6, and TGFβ1)." (PMID 20302663, 2010). "Quercetin can significantly improve lung function in pulmonary fibrosis models by enhancing cell viability, reducing the production of inflammatory cytokines Tumor Necrosis Factor-alpha (TNF-α), Interleukin-6 (IL-6), Interleukin-8 (IL-8), and inhibiting apoptosis." (PMID 40697927, 2025). "However, after treatment with LP03, the concentrations of TNF-α, IL-6, and IL-1β were notably reduced, highlighting the protective effect of LP03 against the inflammatory response in BLM-induced pulmonary fibrosis." (PMID 40994978, 2025). "The levels of IL-6 were significantly higher in sarcoidosis patients with fibrotic outcome than those without, which is in line with the previous finding that IL-6 has a protective role against lung fibrosis." (PMID 40725075, 2025). "Potential Mechanisms: 1) Plasma cell-derived cytokine production: Malignant plasma cells in MM produce multiple cytokines (IL-6, TNF-α, IL-1β) that may trigger pulmonary fibrosis through Th2-mediated immune responses." (PMID 41477374, 2025). "IL-6 and TNF-α are proinflammatory factors but also inducers of pulmonary fibrosis." (PMID 38914619, 2024). "Additionally, BAFF also promotes pulmonary interstitial fibrosis by acting as a potent inducer of TIMP-1, α-SMA, CCL2, and IL-6." (PMID 38637830, 2024). "The drug group exhibited significantly elevated expression of transforming growth factor β (TGF-β), hydroxyproline (HYP; which can indicate the degree of pulmonary fibrosis), Tumor Necrosis Factor α (TNF-α), and Interleukin 6 (IL-6) gene compared to the control group." (PMID 37580529, 2023). "TNF-α, TGF-β1, IL-6, MCP-1, and MMP-7 are inflammatory mediators and profibrotic factors involved in lung tissue damage and play a significant role in the initiation and progression of pulmonary fibrosis." (PMID 37047142, 2023). "JWH133 activated CB2R regulating the inflammatory response, and subsequently reduced pulmonary fibrosis in mice.The ELISA results showed significantly higher levels of inflammatory markers TNF-α, IL-6, and IL-1β in the serum of the BLM group, which decreased after the administration of JWH133." (PMID 37957604, 2023). "Results showed that LPSF/GQ-16 not only influenced the PBMCs’ production of IL-2, IL-4, IL-6, IL-17A, TNF, and IFN-γ, but also reduced skin thickening, downregulated biomarkers of skin and lung fibrosis, as well as decreased the activation of immune cells in the experimental model." (PMID 37833885, 2023). "Although it is possible that IL-6 will play a role in lung fibrosis, both IL-6 and CRP are non-specific for ILD, as their levels can be elevated in almost any inflammatory condition." (PMID 37892818, 2023). "Iguratimod can inhibit the expression of TNF-α, IL-1, IL-6 and MMP-9 to reduce bleomycin-induced alveolar inflammation and pulmonary fibrosis in mice, suggesting that iguratimod may become an effective strategy for the treatment of pulmonary fibrosis." (PMID 37809072, 2023).
pulmonary fibrosis (continued). "In bleomycin-induced pulmonary fibrosis, activation of the cGAS-STING signaling pathway not only leads to the production of numerous SASP factors such as IL-6, IL-8, and the upregulation of cell cycle-related factors p16 and p21, but also increased secretion of inflammatory factors like IFN-β." (PMID 37965345, 2023). "Additionally, during infection, levels of pro-inflammatory cytokines such as IL-1 (interleukin) and IL-6 increase as a result of the virus binding to TLR, which eventually leads to inflammation, fever, and lung fibrosis." (PMID 36980393, 2023). "Similarly, in an established model of lung fibrosis, RP-832c significantly decreased lung fibrosis and significantly decreased inflammatory cytokines TNF-α, IL-6, IL-10, IFN-γ, CXCL1/2, and fibrosis markers TGF-β1 and MMP-13." (PMID 37174654, 2023). "In addition, CCP exhibited potent anti-pulmonary fibrosis activity in vivo by reducing collagen deposits and down-regulated the expression of TGF-β1 and IL-6." (PMID 37298817, 2023). "Indeed, one main etiology of pulmonary fibrosis is acute and/or chronic inflammation via the release of lung proinflammatory cytokines and chemokines (such as TNF-α, IL-1β, IL-6, and IL-8) along with NF-κB." (PMID 36830999, 2023). "An aberrant activation of IL6/JAK/STAT3 and tofacitinib gene signatures was found in biopsies from SSc patients and Tofacitinib was reported to be effective in preventing bleomycin-induced skin and lung fibrosis in the animal models." (PMID 36556466, 2022). "Meanwhile, the preclinical study demonstrated that the blockade of IL-6, CD47, and PD-L1 together could ameliorate pulmonary fibrosis by increasing phagocytosis of profibrotic fibroblasts and by eliminating suppressive effects on adaptive immunity." (PMID 36544757, 2022). "In addition to IL-6– and IL-1–driven pathways, IPA also identified active processes of pulmonary fibrosis and hypoxia-induced gene regulation in infected lung tissue of aged mice." (PMID 36129445, 2022). "IL-6 was shown to be upregulated in IPF patients 43 and animal models of pulmonary fibrosis 44; furthermore, JAK2 and STAT3 were increased and activated in the hyperplastic alveolar cells of IPF patients 42, which suggested that IL-6/JAK/STAT3 plays a role in lung fibrosis." (PMID 36147459, 2022). "For instance, IL-6, a soluble mediator with a pleiotropic effects, can activate the STAT3/SMAD signaling pathway by binding to IL-6R in order to induce ECM expression in lung fibroblasts, thereby exacerbating bleomycin-induced lung fibrosis." (PMID 36299447, 2022). "As we expected, IL-6, TNF-α, CRP, and D-dimer levels were all reduced after lenalidomide treatment, which is consistent with previous findings that lenalidomide attenuated IL-6 and TNF-α secretion in a pulmonary fibrosis model and mantle cell lymphoma." (PMID 35967862, 2022). "STAT3 is a receptor for the inflammatory cytokine IL-6, which stimulates TGF-1 and may play a role in the development of pulmonary fibrosis in patients suffering from COVID-19." (PMID 35444538, 2022). "Down-regulates MDA, TNF-α and IL-6 expression; increases SOD activity; inhibits epithelial–mesenchymal transition; and slows the development of pulmonary fibrosis by inhibiting oxidative stress and inflammation in the lung tissues of mice with pulmonary fibrosis." (PMID 35566359, 2022). "All these indicate that TGF-β, TNF-α, IL-1β, IL-6, IL-13, ACE2 and autophagy inhibition may be the key factors in pulmonary fibrosis induced by SARS-CoV-2." (PMID 34876129, 2021). "In this experiment, we found that Yifei decoction combined with MitoQ could significantly reduce the expression of IL-6, IL-1β, TNF-α, and MDA and increase the activity of GSH-Px and SOD in lung tissue of rats with pulmonary fibrosis induced by bleomycin." (PMID 34135982, 2021).
pulmonary fibrosis (continued). "Notably, the suppressive effect of SF-MSCs on circulating IL-6 at day 14, regarded as the late phase of BLM-induced pulmonary fibrosis, was extremely strong, resulting in levels as low as those in control mice without BLM treatment." (PMID 34530920, 2021). "In brief, actions of some of the assessed interleukins in the context of pulmonary fibrosis can be summarized as follows: IL1ꞵ (pro-fibrotic), IL4 (pro and anti-fibrotic), IL6 (pro and anti-fibrotic), IL8 (pro-fibrotic), IL10 (anti-fibrotic), IL12 (anti-fibrotic), and IL13 (pro-fibrotic)." (PMID 34960806, 2021). "The successful establishment of a mouse model with T2DM‐associated PTB was confirmed as inflammatory cell infiltration and increased pulmonary fibrosis, as well as increased production of pro‐inflammatory factors including TNF‐α, IL‐6 and IL‐1β in mouse lung tissues." (PMID 33089914, 2020). "In addition, the inflammatory cytokines, including IL-6 and TNF-α, were markedly elevated in the mice lung tissues of the pulmonary fibrosis model and were dramatically inhibited by Hyp." (PMID 33192501, 2020). "Moreover, it has been described that IL6, TNF-α, and IL-1β lead to activation of the NF-kB pathway, which is the major controller of pulmonary fibrosis and epithelial–mesenchymal transition, in response to chronic inflammation." (PMID 32660140, 2020). "IL-6 was shown to be elevated in lungs of IPF patients and in mouse models of pulmonary fibrosis." (PMID 32070329, 2020). "The levels of IL-1, IL-6, and TNF-α in the bleomycin-induced mouse pulmonary fibrosis model were higher than those in the control group, while RC28-E treated mice showed a significant reduction in the levels of the proinflammatory cytokines IL-1, IL-6, and TNF-α in a concentration-dependent manner." (PMID 31652997, 2019). "The pro-fibrotic cytokine IL-6, capable of fibroblast activation and promotion of collagen synthesis, was found to be substantially increased in IL-12p40−/− mice, and was suggested to promote BLM-mediated lung fibrosis." (PMID 30315190, 2018). "In our study, we found that BALF TNF-α and IL-6 levels and lung TNF-α and IL-6 mRNA were markedly increased in the WT BLM group mice, indicating that 5-HT might promote the production of cytokines in pulmonary fibrosis." (PMID 29849496, 2018). "Consistent with an independent role of p-JAK2 in lung fibrosis, we observed that p-JAK2 inhibition in ATII and lung fibroblasts from IPF patients partially reduced the mesenchymal-myofibroblast transformation induced by TGF-β1 and IL-6/IL-13." (PMID 29409529, 2018). "Here, we also demonstrate that CXCL10, CCL4, CXCL8 and IL-6-producing classical, non-classical monocytes and mDC profile identify a subset of patients characterized by the presence of lung fibrosis and decreased lung function." (PMID 29127442, 2018). "Here, our results demonstrated that the expressions of fibrosis-related cytokines IL-6 and myofibroblast markers COL1A1 were significantly increased in the supernatant of TGF-β1 induced MLF, serum, and BALF in mice with BLM-induced pulmonary fibrosis, especially in BLM 42d group." (PMID 28420366, 2017). "However, after PFD treatment, the levels of COL1A1and IL-6 were significantly decreased, indicating that PFD inhibited the production of a pro-fibrosis factor and the development of lung fibrosis." (PMID 28420366, 2017). "Also, BLM up-regulated COL1A1 and IL-6 levels in serum and BALF of mouse with pulmonary fibrosis, and level of COL1A1 in BLM 42d is higher than BLM 14d group." (PMID 28420366, 2017). "After PFD treatment, COL1A1and IL-6 levels in supernate of MLF, serum, and BALF as well as ROS in lung tissues and MDA in serum and BALF from a mouse with pulmonary fibrosis were significantly decreased, and the infiltration of lung inflammatory cells and fibrosis degree were alleviated." (PMID 28420366, 2017).
pulmonary fibrosis (continued). "The mechanisms influencing IL-6 expression in pulmonary fibrosis are not yet known, and epigenetic control of IL-6 expression is, in general, poorly understood." (PMID 28194150, 2016). "The changes in IL-6-producing and -acting cells between different injury stages may at least support a bidirectional role of IL-6 in BLM-induced lung fibrosis." (PMID 26289430, 2015). "IL-6 and TNF-α also play important roles in the pathogenesis of pulmonary fibrosis." (PMID 25216247, 2014). "After a study on mouse lung tissue and lavage fluid, we found that dexamethasone can reduce inflammatory cell infiltration and decrease inflammatory cytokines related to lung fibrosis closely such as TNF-α, IL-6, and TGF-β1 protein expression in BALF in the 4th week, compared with the RT group." (PMID 24744681, 2014). "As lung myofibroblasts appear to play a role in lung fibrosis, DHA may be mitigating the development of fibrosis by inhibiting bleomycin induced IL-6." (PMID 24742272, 2014). "From our findings, IL-6 from cancer cells could induce COL1A1 and α-actin expression in lung fibroblast cells, suggesting IL-6 was likely one of the important factors for lung fibrosis." (PMID 23592411, 2013). "Dong Z and co-workers recently showed that ATRA is able to decrease the expression of interleukin-17A (IL-17A), IL-6, and TGF-β1, and could alleviate bleomycin-induced pulmonary fibrosis in C57BL/6 male mice." (PMID 23344030, 2012). "The medium dose (1.0 × 104 cells) showed the most pronounced effects on pulmonary fibrosis and collagen deposition, while significantly suppressing pro-inflammatory cytokines, including interleukin-1β and interleukin-6; however, this effect was not consistent across all measured outcomes." (PMID 41155309, 2025). "Some treatments include mast-cell stabilizers to control their access to inflamed tissue and consequent cytokine production (IL-1, IL-6 and TNF-a); moreover, it has been suggested that treatment for idiopathic pulmonary fibrosis could benefit patients with PC19-PF." (PMID 40332501, 2025). "Pulmonary fibrosis (PF) is a chronic and progressive lung disease, It is characterized by chronic inflammation, characterized by the release of cytokines such as transforming growth factor beta (TGF-β) and interleukin 6 (IL-6), triggered by repeated alveolar damage." (PMID 40860474, 2025). "Lastly, several cytokines involved in TH2 cell recruitment and fibrosis (IL-6, eotaxin, PDGF-ββ, IL-10, IL-1β) were released from macrophages in vitro and correlated with in vivo BAL response, which aligns with KE4 (TH2 cell activation) in the lung fibrosis AOP." (PMID 38509617, 2024). "In addition, BAFF antagonists reduce skin and pulmonary fibrosis in scleroderma models by reducing IL-6+ Beffs rather than IL-10+ Bregs." (PMID 39080112, 2024). "Ample evidence supports that SiO2 activates inflammatory cytokines such as IL-1β, IL-6, TGF-β, TNF-α, growth factors, and CCL and promotes pulmonary fibrosis, suggesting that increased inflammatory cytokine levels may be used as typical biomarkers for the clinical diagnosis of silicosis." (PMID 38515835, 2024). "Therefore, we hypothesized that elevated IL-6 leads to the subpopulation conversion of Treg to Th17 cells, which increases the production of IL-17 and TGF-β and promotes lung fibrosis." (PMID 38263193, 2024). "In addition, by inhibiting the activation of NF-κB in macrophages and lymphocytes, the expression levels of nitric oxide and tumor necrosis factor-α (TNF-α), interleukin (IL-1β), IL-6, transforming growth factor-β (TGF-β) and TNF in pulmonary fibrosis are reduced to prevent oxidative damage." (PMID 37089962, 2023). "In this study, the administration of hESC-MSC-IMRCs or hESC-MSC-IMRC-CM exhibited an ability to suppress TNF-α, IL-1β, and IL-6 release in lung tissues of BLM-challenged mice, suggesting that hESC-MSC-IMRCs or hESC-MSC-IMRC-CM could mitigate pulmonary fibrosis by relieving inflammatory responses." (PMID 36830999, 2023).